RNU6-968P (RNA, U6 small nuclear 968, pseudogene)
Gene: Small nuclear RNA gene on chromosome 1 (235,915,415 to 235,915,521, forward strand). Ensembl gene ENSG00000206803.
Homologues: Orthologues: chimpanzee U6 (96% identical), mouse Gm25598 (86% identical), rabbit U6 (86% identical), rat LOC120101949 (85% identical). Paralogues in human: RNU6-39P (94% identical), RNU6-45P (94% identical), RNU6-12P (93% identical), RNU6-13P (93% identical), RNU6-16P (93% identical), RNU6-32P (93% identical), RNU6-1 (93% identical), RNU6-17P (93% identical), RNU6-18P (93% identical), RNU6-2 (93% identical), RNU6-3P (93% identical), RNU6-4P (93% identical), and 1288 more.